LRRC42 (leucine rich repeat containing 42)
Synonyms: MGC8974; dJ167A19.4
Tractability: PROTAC: ubiquitination databases record sites on it.
Gene: Protein-coding gene on chromosome 1 (53,946,045 to 53,968,168, forward strand). Ensembl gene ENSG00000116212.
Subcellular location (Human Protein Atlas): Nucleoplasm
Gene Ontology:
Cellular component: nucleoplasm
Genetic constraint (gnomAD): Loss-of-function variants: 27 observed, 31.78 expected, observed/expected ratio (o/e) 0.85, 90% interval 0.62 to 1.17. The upper end of that interval is the gene's LOEUF score, 1.17, which puts it in group 5 of 6, group 1 being the genes least tolerant of losing a copy. Missense variants: 479 observed, 463.02 expected, observed/expected ratio (o/e) 1.03, 90% interval 0.96 to 1.12. Synonymous variants: 188 observed, 181.36 expected, observed/expected ratio (o/e) 1.04, 90% interval 0.92 to 1.17.
Homologues: Orthologues: chimpanzee LRRC42 (99% identical), macaque LRRC42 (96% identical), pig LRRC42 (95% identical), dog LRRC42 (92% identical), rabbit LRRC42 (88% identical), rat Lrrc42 (88% identical), guinea pig LRRC42 (87% identical), mouse Lrrc42 (87% identical), tropical clawed frog lrrc42 (49% identical), zebrafish lrrc42 (45% identical).
Diseases named in the same sentence as LRRC42 in open-access papers:
LRRC42 is named in the same sentence as 1 disease in open-access papers, as found by Europe PMC text mining. Sharing a sentence is not in itself a finding about the gene and the disease. The quoted sentences say what the papers report.
cancer (1 paper, 2020). A tumor composed of atypical neoplastic, often pleomorphic cells that invade other tissues. "When examining the top 100 gene pairs, BSDC1, C3orf14, CDR2L, LRRC42, MEOX2, NRG2, and PLEKHA6, and SCARF1 were consistently identified by feature selection methods to be associated with cancer status." (PMID 33087122, 2020). "C3orf14, CDR2L, LRRC42, MEOX2, NRG2, and SCARF1 have been previously associated with cancer." (PMID 33087122, 2020). "Interestingly, C3orf14, CDR2L, LRRC42, MEOX2, NRG2, and SCARF1 are known carcinogenic genes, while BSDC1 and PLEKHA6 have not been described in previous cancer literature." (PMID 33087122, 2020).